PAX1 (paired box 1)
Diseases named in the same sentence as PAX1 in open-access papers (continued):
Sharing a sentence is not in itself a finding about the gene and the disease.
cervical cancer (continued). "Recently, an increasing number of studies have confirmed PAX1 methylation as a promising biomarker in cervical cancer based on its excellent discriminatory ability between high‐grade cervical lesions and normal tissues, resulting in a reduced necessity for referral for colposcopy and biopsy." (PMID 30636379, 2019). "In scrapings for cervical cancer, analyses indicated that PAX1 is silenced by hypermethylation." (PMID 30636379, 2019). "Loss of PAX1 expression, however, through DNA methylation, may disrupt this balance, leading to cancer development, supporting the further study of PAX1 DNA methylation as a biomarker for cervical cancer detection." (PMID 31235851, 2019). "The methylation of the paired box-1 (PAX1) gene in cervical cancer was firstly reported in 200816." (PMID 31235851, 2019). "Previous studies have reported that PAX1 methylation testing is a potential biomarker for the screening of cervical cancer with a sensitivity and specificity greater than 80% in the detection of grade III or higher cervical intraepithelial neoplasia (CIN3+) lesions." (PMID 28241446, 2017). "Previous studies have demonstrated that the methylation status of PAX1/ZNF582 may serve as useful biomarkers for the detection of cervical cancer." (PMID 28241446, 2017). "Thus, PAX1 gene methylation is a promising biomarker of radiosensitivity of cervical cancer." (PMID 37533109, 2023). "However, its prognostic value after radiotherapy for locally advanced cervical cancer is unknown, so this study aimed to investigate the value of PAX1 gene methylation for predicting the sensitivity of radiotherapy for cervical cancer." (PMID 37533109, 2023). "PAX1 reexpression was observed in cervical cancer cell lines after treatment with curcumin and resveratrol, may be due to their effect on histone deacetylase mediated through downregulation of UHRF1 which can regulate both DNA methylation and histone acetylation." (PMID 36393845, 2022). "Moreover, incorporating the detection of PAX1 methylation (PAX1m) with an hrHPV test could improve the efficacy of cervical cancer screening." (PMID 36678411, 2022). "However, few studies have evaluated the changes in PAX1 gene methylation status during radiotherapy, and it is unclear whether it can predict the therapeutic response in cervical cancer." (PMID 34335930, 2021). "Moreover, reactivation of PAX1 may overcome the failure of current target therapies targeting single kinases in cervical cancer treatment." (PMID 31235851, 2019). "PAX1, MAL, and CADM1 have been proposed as tumour suppressor genes involved in the development and progression of cervical cancer." (PMID 40564169, 2025). "Many studies previously identified that paired box gene 1 (PAX1), a methylation-silenced gene observed in cervical cancer, can be used as an auxiliary biomarker for clinical examination of cervical cancer to improve the effectiveness of screening." (PMID 37533109, 2023). "Furthermore, we tested whether PAX1 could induce radioresistance in cervical cancer cell lines." (PMID 37533109, 2023). "The use of differential methylation hybridization using a pilot methylation array allowed the identification of SOX1, NKX6-1, PAX1, WT1, and LMX1A as frequently methylated genes in cervical cancer and precursor lesions." (PMID 34790573, 2021). "Therefore, the reasonable sensitivity (0.72 vs 0.89) and high specificity (0.88 vs 0.60) of PAX1 methylation make it a promising predictive marker of the short-term efficacy of CCRT in cervical cancer, and combining it with MRI may further enhance the accuracy of therapeutic monitoring." (PMID 34335930, 2021). "Here, we propose a screening strategy for cervical cancer that combines using the HPV testing and PAX1‐methylation analysis as triage tests according to current evidence." (PMID 30636379, 2019).
cervical cancer (continued). "The methylation of most HPV types except HPV52 also works together with the methylation of host genes including PAX1 and SOX1, which leads to a more significant result of cervical cancer/CIN." (PMID 29850477, 2018). "Combining parallel testing of PAX1, DAPK1, RARB, WIF1, and SLIT2 DNA methylation and HPV DNA increases specificity to identify cervical cancer and achieves better precision than single HPV DNA testing does." (PMID 29850477, 2018). "A high frequency of promoter methylation of PAX1 and ZNF582 genes has been detected in cervical cancer." (PMID 28241446, 2017). "Algorithms that include molecular tests (methylated PAX1, ZNF582, and HPV16/18) in combination with clinical examination findings provide an effective method to increase the accuracy of diagnosis for cervical cancer." (PMID 27293491, 2016). "In previous studies, we discovered that SOX1, NKX6-1, PAX1, WT1, and LMX1A are highly methylated in cervical cancer." (PMID 22815913, 2012). "The differential methylation hybridization (DMH) using a pilot methylation array identified SOX1, NKX6-1, PAX1, WT1, and LMX1A as frequently methylated genes in cervical cancer and its precursor lesions." (PMID 22815913, 2012). "In addition to PAX1, other methylation-based biomarkers such as SOX1 and ZNF582 have shown moderate-to-high sensitivity and specificity for detecting HSIL and cervical cancer." (PMID 41229153, 2025). "We observed a significant higher frequency of subjects having promoter methylation signals at the four genes, RARB (94.0%), CADM1 (76.5%), DAPK1 (64.1%), and PAX1 (96.5%), in patients with invasive cervical cancer compared to the subjects without cancer." (PMID 33718129, 2021). "Subsequent studies demonstrated that the PAX1 methylated level could accurately distinguish high-grade CIN lesions and cervical cancer." (PMID 34335930, 2021). "In HPV‐positive patients, the detection of PAX1 methylation is necessary for diagnosis of CIN3+ lesions and will greatly benefit accurate cervical cancer screening, identify women that require treatment, and reduce unnecessary referrals for colposcopy and biopsy." (PMID 30636379, 2019). "On the other hand, PAX1 and PAX4 are silenced by DNA methylation in ovarian and cervical cancers and in melanoma, and may function as tumor suppressors." (PMID 28241446, 2017). "Additionally, the pooled PLR was 3.5, suggesting that patients with cervical cancer were 3.5 times more likely to test positive for PAX1 methylation compared to those without disease." (PMID 41229153, 2025). "In addition, this study mainly focused on the application of PAX1 gene methylation detection in cervical lesion screening, without in-depth exploration of its potential value in cervical cancer treatment monitoring and prognosis evaluation." (PMID 40777030, 2025). "Various host cell methylated genes such as SOX1, PAX1, JAM3, EPB41L3, CADM1, and MAL have been investigated for predicting cervical lesions, with PAX1 gene methylation showing the most significant correlation with the progression of cervical intraepithelial neoplasia and cervical cancer occurrence." (PMID 39155349, 2024). "At present, there is still a lack of research on whether PAX1 hypermethylation can predict the radiotherapy sensitivity of cervical cancer." (PMID 37533109, 2023). "We selected 125 patients with primary cervical cancer who underwent concurrent chemo-radiotherapy as the study population, quantitative methylation-specific polymerase chain reaction (QMSP) was used for detecting PAX1 methylation status of cervical exfoliated cells." (PMID 37533109, 2023). "Reactivation of PAX1 due to promoter hypomethylation has been achieved through silencing of DNMT1 in Hela and Siha cell lines, suggesting DNMT1 might be the methytransferase responsible for the hypermethylation level of PAX1 in cervical cancer cells." (PMID 36393845, 2022).
cervical cancer (continued). "Consequently, we overexpressed PAX1 in two cervical cancer cell lines, HeLa and SiHa, and found that it did not significantly inhibit malignant phenotypes, including proliferation, migration, and invasion, in vitro, and tumor growth, in vivo." (PMID 31235851, 2019). "Consistent with the reports in cervical cancers, we observed in the current study that PAX1 methylation testing had a 100% sensitivity and a 78.6% specificity in the detection of ESCC tumors, indicating that PAX1 methylation is a valuable biomarker for ESCC diagnosis." (PMID 28241446, 2017).
cervical intraepithelial neoplasia (9 papers, 2014 to 2026). "Diagnostic Performance of PAX1 Methylation in CIN Detection Receiver operating characteristic (ROC) curve analysis of PAX1 methylation demonstrated robust diagnostic performance for cervical intraepithelial neoplasia (CIN) detection." (PMID 40777030, 2025). "The effectiveness of PAX1/JAM3 methylation in detecting high‐grade cervical intraepithelial neoplasia (CIN) was compared to traditional screening methods." (PMID 41239544, 2026). "The genes for sex-determining region Y-box 1 (SOX1) and paired box gene 1 (PAX1) have been reported as potential methylation biomarkers and studies have demonstrated their promise in the detection of cervical intraepithelial neoplasms (CIN) grade 3 and worse lesions (CIN3+) 28,35." (PMID 24799352, 2014). "The differences in the methylation statuses of three genes, PAX1, SOX1, and ZNF582, were evident between normal control samples and cervical intraepithelial neoplasm (CIN) I–III as well as SCC samples." (PMID 33003642, 2020). "Several studies examining paired boxed gene 1 (PAX1) and zinc finger protein 582 (ZNF582) have reported their potential utilization as highly sensitive biomarkers for detection of cervical intraepithelial neoplasia at grade 3 or higher (CIN3+)." (PMID 27293491, 2016). "The delta Cp of methylated PAX1 and ZNF582 was obtained via quantitative methylation-specific PCR in a training set (57 CIN2− and 43 cervical intraepithelial neoplasia ≥grade 3 (CIN3+) women), and the individual and combination gene sensitivities and specificities were determined." (PMID 27293491, 2016).
otofaciocervical syndrome type 2 (9 papers, 2020 to 2024). "PAX1 mutations are identified in Severe Combined Immunodeficiency (SCID) patients with Otofaciocervical Syndrome Type 2 (OTFCS2)." (PMID 38664733, 2024). "Paired box 1 (PAX1) deficiency has been reported in a small number of patients diagnosed with otofaciocervical syndrome type 2 (OFCS2)." (PMID 37689091, 2023). "DiGeorges syndrome is caused by a microdeletion of the TBX1-containing chromosome region 22q11.2, nude SCID by mutations in the FOXN1 gene and Otofaciocervical Syndrome type 2 in the PAX1 gene." (PMID 35844523, 2022). "Autosomal recessive PAX1 mutations cause a rare syndrome called otofaciocervical syndrome type 2 (OTFCS2)." (PMID 33257998, 2021). "Other genes, implicated in thymic organogenesis include FOXN1, associated with Nude SCID syndrome, PAX1, associated with Otofaciocervical Syndrome type 2, and CHD7, one of the genes implicated in CHARGE syndrome." (PMID 32922396, 2020). "Importantly, there are more and more reports recent years showed PAX1 deficiency is associated with otofaciocervical syndrome type 2 (OTFCS2) patients displayed severe combined immunodeficiency (SCID) phenotypes due to altered thymus development." (PMID 38664733, 2024). "PAX1 homozygous loss-of-function variants are causative of otofaciocervical syndrome 2 with T-cell deficiency (OTFCS2) (#615560 OMIM), which may include a severe combined immunodeficiency (SCID) due to abnormal thymic epithelium development." (PMID 35407632, 2022). "Biallelic homozygous nonsense or hypomorphic missense mutations in PAX1 cause otofaciocervical syndrome type 2 (OTFCS2), a similar but more severe multi-system disorder that can be accompanied by severe combined immunodeficiency due to thymic aplasia." (PMID 35879406, 2022). "Importantly, recent studies identified quite some cases of PAX1 mutations associated Severe Combined Immunodeficiency (SCID) patients with Otofaciocervical Syndrome Type 2 (OTFCS2)." (PMID 38664733, 2024). "Biallelic hypomorphic or loss of function variants in PAX1 have been described in several families with otofaciocervical syndrome type 2 (OTFCS2; MIM 615560)." (PMID 35879406, 2022). "Notably, there are quite some PAX1 mutants identified in Severe Combined Immunodeficiency (SCID) patients with Otofaciocervical Syndrome Type 2 (OTFCS2)." (PMID 38664733, 2024).
cervical (7 papers, 2023 to 2026). "The aim of this study was to evaluate the diagnostic performance of PAX1 methylation in detecting cervical lesions, including HSIL and cervical squamous cell carcinoma (CSCC), by using real-time PCR in a clinical cohort." (PMID 41229153, 2025). "In this study, we evaluated the relationship between cervical lesions with various histopathological characteristics and p16/ki67 immunohistochemical staining and PAX1/ZNF582 methylation in high-risk HPV-positive women." (PMID 39304838, 2024). "In this study, we evaluated the relationship between cervical lesions with various histopathological characteristics and p16/ki67 immunohistochemical staining and PAX1/ZNF582 methylation in HR-HPV-positive women." (PMID 39304838, 2024). "Using prospective time-to-event data, we detected associations between CADM1-, DAPK1-, PAX1-, and RARB-related CpGs and cervical disease progression, and we identified novel progression-associated CpGs." (PMID 37932662, 2023). "The PAX1/JAM3 methylation panel could serve as a triage tool for CC among women undergoing evaluation for cervical disease, particularly in postmenopausal patients and may enhance colposcopy by providing more accurate lesion diagnosis." (PMID 41239544, 2026). "The primary strength of this study was the inclusion of different grades of cervical lesions, i.e., cervicitis, CIN1, CIN2, CIN3, and cervical SCC, enabling a comprehensive analysis of the relationship among PAX1/ZNF582 methylation, p16/Ki67 immunohistochemical scores, and cervical lesions." (PMID 39304838, 2024).
oral cancer (6 papers, 2017 to 2025). "A high level of PAX1 methylation induces tumorigenesis, including oral cancer and cervical cancer." (PMID 34359370, 2021). "Hypermethylated PAX1 and ZNF582 are effective biomarkers for detecting oral cancer and oral dysplasia, and for predicting the recurrence of oral cancer." (PMID 40256126, 2025). "ZNF582 and PAX1 were initially selected from a multi-gene panel of SCC type cancers that included ZNF582, PAX1, SOX1, NKX6.1, and PTPRR genes; these were later developed into a methodology using oral scrapings for the detection of oral dysplasia and oral cancer." (PMID 34359370, 2021).
otofaciocervical syndrome (6 papers, 2015 to 2026). "Mutations in PAX1 cause otofaciocervical syndrome, characterized by facial dysmorphology, including specific nasal features such as a sunken nasal root and excessive narrowing." (PMID 27560520, 2016). "Also, a mutation in PAX1 has been proposed to cause otofaciocervical syndrome in humans." (PMID 25859222, 2015). "For example, otofaciocervical syndrome (OTFCS) is inherited in an autosomal recessive pattern, and can arise as a result of homozygous PAX1 mutations." (PMID 38473380, 2024). "Pathogenic variants in PAX genes underlie diverse congenital disorders such as aniridia (PAX6), renal coloboma syndrome (PAX2), otofaciocervical syndrome with immunodeficiency (PAX1), Waardenburg syndrome (PAX3), maturity-onset diabetes of the young (PAX4), and tooth agenesis (PAX9)." (PMID 41751498, 2026). "Otofaciocervical syndrome (OTFCS) is a rare group disorder that is subclassified into two types: autosomal recessive OTFCS2 (MIM: 615,560) and autosomal dominant OTFCS1 (MIM: 166,780) due to gene mutations in PAX1 and EYA1, respectively." (PMID 37924468, 2023).
squamous intraepithelial lesion (6 papers, 2019 to 2025). "The diagnostic accuracy of PAX1 methylation for detecting high-grade squamous intraepithelial lesions (HSIL) and cervical squamous cell carcinoma (CSCC) was assessed." (PMID 41229153, 2025). "The results of this experiment revealed that PAX1 nuclear expression was weak in normal cervix, moderate in low-grade squamous intraepithelial lesion (LSIL), strongest in high-grade squamous intraepithelial lesion (HSIL), but weak in invasive cancer cells." (PMID 31235851, 2019). "Moreover, several studies have demonstrated that PAX1 methylation increases following increased disease grade: PAX1 methylation in SCC > high − grade squamous intraepithelial lesion (HSIL) > low − grade squamous intraepithelial lesion (LSIL) > normal tissue." (PMID 33376722, 2020). "Our previous study confirmed SOX1 and PAX1 methylation as promising screening biomarkers in cervical neoplasia, mainly in high-grade squamous intraepithelial lesions and SCC, because of its remarkable discriminating ability between normal tissues and high-grade cervical lesions." (PMID 33376722, 2020). "Several studies found that PAX1 methylation increased along with increased disease grade in the following order: PAX1 methylation in squamous cell carcinoma (SCC) > high‐grade squamous intraepithelial lesion (HSIL) > low‐grade squamous intraepithelial lesion (LSIL) > normal tissue." (PMID 30636379, 2019).
combined immunodeficiency (5 papers, 2022 to 2024). A broad classification of inherited disorders presenting at birth that affect both the cell-mediated and humoral aspects of the immune response. "PAX1 deficiency has since been classified as an inborn error of immunity characterized by combined immunodeficiency (CID)." (PMID 37689091, 2023).
esophageal squamous cell carcinoma (5 papers, 2017 to 2025). Esophageal squamous cell carcinoma (ESCC) is a type of esophageal carcinoma (EC) that can affect any part of the esophagus, but is usually located in the upper or middle third. "The hypermethylated PAX1 promoter in esophageal squamous cell carcinoma suggests PAX1 as a tumor suppressor gene, highlighting its multifaceted roles in the human body." (PMID 37924468, 2023). "In esophageal squamous cell carcinoma (ESCC), PAX1 has also been identified as a hypermethylated gene." (PMID 40699796, 2025). "In Esophageal Squamous Cell Carcinoma (ESCC), aberrant hypermethylation of ZNF582 and PAX1 have been demonstrated using quantitative methylation-specific PCR with levels at 21% versus 0% for tumor and peri-tumor normal tissues, respectively." (PMID 33178175, 2020). "In the present study, we investigated the methylation status of PAX1 and ZNF582 genes in esophageal squamous cell carcinoma (ESCC) tissues." (PMID 28241446, 2017).
scoliosis (5 papers, 2014 to 2024). A congenital or acquired spinal deformity characterized by lateral curvature of the spine. "A kinky tail phenotype has been observed for several genes associated with scoliosis, including Wnt3a,48Axin1,49,50Sox9,51 and Pax1." (PMID 38461417, 2024). "MO knockdown of either Pax1 or Pax9 causes defects in the neural arch and scoliosis and double knockdown revealed that Pax1 and Pax9 function synergistically in sclerotome development." (PMID 25197636, 2014). "Moreover, another spontaneous mutant mouse, called scoliosis (sco), carries a new allele of Pax1 (un-i, undulated intermediate)." (PMID 36393845, 2022). "Homozygous sco mice show a mild form of the known phenotypes of other Pax1 mutants and have a lumbar scoliosis and kinky tails in adults." (PMID 36393845, 2022). "The spinal anomalies observed in Pax1 mouse mutants recapitulates a congenital scoliosis phenotype, although mutations in human PAX1 are not clearly correlated with this condition." (PMID 25784220, 2015).
colorectal cancer (4 papers, 2017 to 2024). A primary or metastatic malignant neoplasm that affects the colon or rectum. "Hypermethylation at the PAX1 promoter and a reduction in PAX1 expression have also been reported in several different carcinomas, including cervical, ovarian, and colorectal carcinoma, although it is unclear whether these are related to tumor initiation, progression, or maintenance." (PMID 38473380, 2024).